GSTM1 (glutathione S-transferase mu 1)
Diseases named in the same sentence as GSTM1 in open-access papers (continued):
Sharing a sentence is not in itself a finding about the gene and the disease.
leukemia (11 papers, 2008 to 2023). A malignant (clonal) hematologic disorder, involving hematopoietic stem cells and characterized by the presence of primitive or atypical myeloid or lymphoid cells in the bone marrow and the blood. "Overall, the GSTM1 null genotype was associated with a significantly increased leukemia risk (OR = 1.24, 95% CI: 1.14–1.34) when all the eligible studies were merged." (PMID 35938012, 2022). "AML-GMP expressed granulocyte–monocyte progenitor markers such as Mpo, Elane, Prss57 and Ctsg22,26,33, along with Gstm1, which has been associated with quiescent, therapy-resistant, leukemia-initiating cells in AML35–37." (PMID 36424441, 2022). "In addition, the GSTM1 null genotype was associated with a significantly increased leukemia risk in Asians (OR = 1.48, 95% CI: 1.30–1.68), Caucasians (OR = 1.14, 95% CI: 1.03–1.26), and Indians (OR = 1.37, 95% CI: 1.01–1.87)." (PMID 35938012, 2022). "The results of the association of the GSTM1 polymorphism with the risk of leukemia." (PMID 35938012, 2022). "Significant associations were considered as “positive” results on the GSTM1 null genotype with leukemia risk in overall populations (FPRP < 0.001 and BFDP = 0.006), Asians (FPRP < 0.001 and BFDP < 0.001), and East Asian population (FPRP < 0.001 and BFDP = 0.002)." (PMID 35938012, 2022). "Overall, the combined effects of the GSTM1 present/null and GSTT1 present/null genotypes were associated with a significantly increased leukemia risk (OR = 1.49, 95% CI: 1.27–1.74)." (PMID 35938012, 2022). "Overall, the individual GSTM1 and GSTT1 null genotypes and combined effects of the two genes were associated with significantly increased leukemia risk in the overall analysis and several subgroup analyses, such as Asians, Caucasians, and so on." (PMID 35938012, 2022). "Fourteen meta-analyses reported the individual effects of the GSTM1 and GSTT1 polymorphisms with leukemia risk." (PMID 35938012, 2022). "Based on biochemical properties described for the GSTM1 present/null and GSTT1 present/null polymorphisms, we expected that the individual and the combined effects of the two genes were associated with the risk of leukemia in any population." (PMID 35938012, 2022). "Then, subgroup analysis was conducted by type of leukemia, and significantly increased acute lymphoblastic leukemia (ALL) (OR = 1.24, 95% CI: 1.09–1.41) and acute myeloid leukemia (AML) (OR = 1.26, 95% CI: 1.09–1.45) risk were also observed for the GSTM1 null genotype." (PMID 35938012, 2022). "Furthermore, previous meta-analyses did not perform the combined effects of GSTM1 present/null and GSTT1 present/null polymorphisms with leukemia risk." (PMID 35938012, 2022). "Furthermore, previous meta-analyses did not observe the combined effects of GSTM1 present/null and GSTT1 present/null polymorphism with leukemia risk." (PMID 35938012, 2022).
acute lymphoblastic leukemia (10 papers, 2008 to 2024). Leukemia with an acute onset, characterized by the presence of lymphoblasts in the bone marrow and the peripheral blood. "A significant rise in acute lymphoblastic leukemia risk was observed in patients with GSTM1 and GSTT1 null genotypes." (PMID 28902850, 2017). "The authors suggested that GSTM1 and GSTT1, but not GSTP1 polymorphisms, were associated with a modest increase in the risk of acute lymphoblastic leukemia and GSTM1/GSTT1 null genotypes could play a role in leukemogenesis." (PMID 28902850, 2017). "It was reported that GSTM1 inhibited dexamethasone-induced apoptosis in a lymphoblastic leukemia cell line." (PMID 39044272, 2024). "The presence of the detoxification enzyme Glutathione S-Transferase mu 1 (GSTM1) inhibits dexamethasone-induced apoptosis in lymphoblastic leukemia through suppression of Bim." (PMID 26405162, 2015). "Acute lymphoblastic leukemia has been associated with GSTM1 null but not GSTT1 null genotypes in Filipino children." (PMID 30803216, 2019). "Besides genetic polymorphisms of CYP1A1, CYP2D6, GSTM1 and GSTT1 associate with acute lymphoblastic leukemia in Indian children." (PMID 28902850, 2017).
atherosclerosis (10 papers, 2014 to 2025). A disease characterized by the build-up of fatty material and calcium deposition in the arterial wall resulting in partial or complete occlusion of the arterial lumen. "This gene has also been studied for association with atherosclerosis, and frequency of atherosclerosis in a GSTM1 polymorphic group were found to be 1.2 times higher than those in the control group in a study from a Brazilian cohort." (PMID 31393916, 2019). "In the present study, a significant difference in GSTM1 genotypedistribution was found between cases and controls and homozygousGSTM1 deletion significantly increased the risk of clinicalmanifestations of atherosclerosis." (PMID 29658969, 2018). "The GSTT1-null genotype and combined GSTT1*0/GSTM1*0 might be potential determinants of susceptibility to advanced atherosclerosis in patients with type 2 diabetes mellitus." (PMID 24423050, 2014). "Studies on smokers showed that people with GSTM1 null genotype develop faster atherosclerosis progression than people with GSTM1 wild type." (PMID 36793931, 2023). "Vitamin E supplementation seems to reduce the atherosclerosis progression better in GSTM1 null genotype individuals." (PMID 36793931, 2023). "Thisstudy demonstrated that the GSTM1 null and combinedGSTM1/GSTT1 null genotypes are susceptibility factors fordevelopment of atherosclerosis in a Serbian population." (PMID 29658969, 2018). "In conclusion, coupled deletions of GSTM1 and GSTT1genes may play a significant role in the etiopathogenesis of atherosclerosis and mayrepresent a useful marker in the prediction of disease susceptibility in Serbs." (PMID 29658969, 2018). "A prospective study in Netherlands confirmed an increased progression of atherosclerosis among smokers lacking the enzyme GSTM1." (PMID 24423050, 2014).
chronic kidney disease (10 papers, 2014 to 2024). Impairment of the renal function secondary to chronic kidney damage persisting for three or more months. "This is because certain studies have indicated that the GSTM1-null genotype is correlated with a higher risk of developing end-stage renal disease and an increased susceptibility to oxidative stress in dialysis patients." (PMID 39063019, 2024). "Deletion of glutathione S-transferase μ1 (GSTM1) is common in populations and has been asserted to associate with chronic kidney disease progression in some research studies." (PMID 31555322, 2019). "An association between loss of GSTM1 and chronic kidney disease (CKD) progression has been reported in the African American Study of Kidney and Hypertension (AASK)." (PMID 31555322, 2019). "The presence of glutathione transferase (GST) M1 null genotype (GSTM1-null) in end-stage renal disease (ESRD) patients is associated with lower overall survival rate in comparison to those with GSTM1-active variants." (PMID 24423050, 2014). "The GSTM1 null mutation is a common polymorphism and has also been associated with the end-stage renal disease of unknown etiology in Mexican patients." (PMID 27975059, 2016). "Two ethnicity-specific genes have been associated with end-stage renal disease of unknown etiology in other populations: apolipoprotein L1 (APOL1) gene in African Americans, and Glutathione S-transferase Mu 1 (GSTM1) null phenotype in the Mexican population." (PMID 36674063, 2023). "Up-regulated GSTM1 was protective to increased oxidative stress in chronic kidney disease." (PMID 34276651, 2021).
endometriosis (10 papers, 2012 to 2023). The growth of functional endometrial tissue in anatomic sites outside the uterine body. "Apart from that, GSTM1-null polymorphism has been associated with increased risk for endometriosis and cervical cancer in reproductive age." (PMID 38068321, 2023). "It is known that the genetic polymorphism of CYP1A1, CYP19, and GSTM1 enzymes, which are responsible for the metabolism of medicines, predisposes to endometriosis." (PMID 33153202, 2020). "It has been shown that expression of GSTM1 differs during menstruation and polymorphisms in the GSTs genes were associated to various endometrial pathologies such as for instance endometriosis." (PMID 31999731, 2020). "Genetic polymorphism occurs within the endometrial tissue, concerning estrogen and progesterone receptors, as well as the polymorphism of the enzymes responsible for the metabolism of drugs (CYP1A1, CYP19, and GSTM1), predisposing to endometriosis." (PMID 33153202, 2020). "Women with GSTM1-null genotype compared to other genotypes recorded a summary OR of 1.96, demonstrating an approximately double risk of endometriosis." (PMID 32143537, 2020). "The endometriosis women with GSTM1 homozygous null genotype had a six- fold increased risk of developing endometriosis (p=0.027; OR=5.76)." (PMID 27351025, 2016). "In the endometriosis group, homozygous women for the GSTM1 null allele showed a six-fold increased risk of endometriosis than the controls." (PMID 27351025, 2016). "A novel finding of the present study was the significant positive association between the null genotype of GSTM1 and endometriosis risk." (PMID 25208225, 2014). "The association between GSTM1 polymorphism and endometriosis was investigated in 25 studies, which included a total of 3330 cases and 3959 controls." (PMID 25208225, 2014). "The result showed that the null genotype of GSTM1 was associated with an increased endometriosis risk (OR = 1.54, 95% CI: 1.30–1.83, P<0.001)." (PMID 25208225, 2014). "To investigate the possible association between the GSTM1 gene null genotype and susceptibility to endometriosis and also its severity, we performed a case-control study in woman of central and southern Iran." (PMID 25242970, 2012). "The role of genetic factors in endometriosis has been assessed and confirmed through numerous familial and twin studies in different populations and several studies have implicated GSTM1 gene as a possible candidate gene for susceptibility to endometriosis." (PMID 25242970, 2012). "In this study, the possible association between the GSTM1 gene null genotype and susceptibility to endometriosis in woman from central and southern Iran was investigated." (PMID 25242970, 2012). "GSTM1 null mutation has been associated with endometriosis in Russian, French, Indian, Chinese, Taiwanese, and Turkish women." (PMID 25242970, 2012). "Moreover, a recent meta-analysis indicated that the GSTM1-null genotype is probably a potential genetic marker for the risk of endometriosis." (PMID 38068321, 2023). "Almost a decade later, two other meta-analysis studies conclude that both GSTT1 and GSTM1 null genotypes could be risk factors for endometriosis but suggest that further studies are needed for confirmation." (PMID 36013572, 2022). "Besides the analysis of CYP1A1, CYP19, and GSTM1 genetic polymorphisms, the latest research concentrates on identifying the significance of the expression level of these genes in endometriosis." (PMID 33153202, 2020). "Our results showed that the GSTM1 null genotype might be associated with the risk of endometriosis in Iranian women." (PMID 27351025, 2016). "Interestingly, susceptibility for endometriosis, which is higly hormone dependent was shown in one study to be negatively correlated to the expression of GSTM1 gene although this was challenged in other studies." (PMID 24324590, 2013).
endometriosis (continued). "They found that women with GSTM1 null phenotype and higher concentrations of PCBs might have an increased susceptibility to endometriosis." (PMID 25242970, 2012). "Several studies have indicated an association between GSTM1 null mutation and endometriosis." (PMID 25242970, 2012). "We performed a case-control study in woman of central and southern Iran to test the hypothesis that the GSTM1 gene null genotype is associated with susceptibility to endometriosis or severity of it." (PMID 25242970, 2012). "Polymorphism of GPX1 198Pro > Leu and CAT-262C > T are both associated with symptomatic endometriosis, and CAT-262C > T and GSTM1 are risk factors for disease’s development." (PMID 36013572, 2022). "In particular, a 2015 meta-analysis by Guo on the association between variants of GST, GSTM1 and GSTT1 genes, which encode for glutathione S transferase, and the development of endometriosis showed a significant increase in risk." (PMID 32143537, 2020). "To compare our findings, we search the PubMed database for studies that examined the association between GSTM1, GSTT1, and GSTP1 313 A/G polymorphisms with endometriosis up to July 2014." (PMID 27351025, 2016). "Briefly, positive and negative results were found in seven and six of these studies, which evaluated the GSTM1 null genotype and endometriosis, respectively." (PMID 27351025, 2016). "Accordingly, we investigated the association between GSTM1, GSTT1 and GSTP1 variations and susceptibility to endometriosis in Iranian women." (PMID 27351025, 2016). "We examined the associations of GSTM1 and GSTT1 null genotypes and GSTP1 313 A/G polymorphisms with endometriosis in an Iranian population." (PMID 27351025, 2016). "Both GSTM1- and GSTT1-null genotypes increased risk of endometriosis (OR = 1.54, 95% CI: 1.30–1.83, P<0.001; OR = 1.41, 95% CI: 1.10–1.82, P = 0.007; respectively)." (PMID 25208225, 2014). "Since then, many studies have investigated the associations between null genotypes of GSTM1 and GSTT1 and endometriosis susceptibility." (PMID 25208225, 2014). "The observation that the null genotypes of GSTM1, GSTT1, and GSTM1-GSTT1 increased the risk of developing endometriosis is biologically plausible." (PMID 25208225, 2014). "In conclusion, this meta-analysis suggests that GSTM1- and GSTT1-null genotypes are associated with an increased risk of endometriosis." (PMID 25208225, 2014). "GSTM1 and GSTT1 polymorphisms have been suggested to be associated with endometriosis by many epidemiological studies." (PMID 25208225, 2014). "Our meta-analysis suggested that there were significant associations between the null genotypes of GSTM1 and GSTT1 and endometriosis." (PMID 25208225, 2014). "Sun-Wei Guo also evaluated the association between GSTM1 and GSTT1 polymorphisms and endometriosis risk by performing a meta-analysis including 14 studies with 1539 cases and 1805 controls." (PMID 25208225, 2014). "Meta-analysis of associations between GSTM1, GSTT1, and GSTM1-GSTT1 polymorphisms and endometriosis." (PMID 25208225, 2014). "This meta-analysis provides evidence that null genotypes of GSTM1 and/or GSTT1 contribute to risk of endometriosis." (PMID 25208225, 2014). "Numerous studies have shown an association between GSTM1 and/or GSTT1 polymorphisms and endometriosis susceptibility." (PMID 25208225, 2014). "This is the first study investigating the association of CAT-262C > T, GPX1 198Pro > Leu, GSTT1, and GSTM1 gene polymorphisms in the Eastern European women population with and without endometriosis, having analyzed a large number of patients." (PMID 36013572, 2022). "The null genotype of GSTM1 was detected significantly higher in the endometriosis group." (PMID 36013572, 2022). "In comparison, our findings indicate that only GSTM1 is correlated with endometriosis." (PMID 36013572, 2022).
endometriosis (continued). "This study suggests that GPX1 198Pro > Leu, CAT-262C > T, and GSTM1 polymorphisms may be risk factors and that the association between the GSTM1-GSTT1 null genotype may play a significant role in endometriosis-associated infertility." (PMID 36013572, 2022). "The null genotype of GSTM1 was significantly higher in the endometriosis group (p < 0.0001)." (PMID 36013572, 2022). "Our results showed that GSTM1 and GSTP1 polymorphisms may be associated with susceptibility of endometriosis in Iranian women." (PMID 27351025, 2016). "According to our knowledge, the results of GSTP1 313 A/G polymorphism and GSTM1 null deletions with the endometriosis are not consistent." (PMID 27351025, 2016). "In conclusion, the GSTM1 and GSTT1 null variations may be associated with the increased risk of endometriosis in Iranian population." (PMID 27351025, 2016). "The aim of this study was to evaluate whether the GSTM1, GSTT1 null genotypes and GSTP1 313 A/G polymorphism are associated with susceptibility to endometriosis." (PMID 27351025, 2016). "A previous meta-analysis conducted by Sun-Wei Guo in 2005 indicated a significant association between the GSTT1-null genotype and endometriosis, however no such association was found between the GSTM1- or GSTM1-GSTT1-null genotypes and endometriosis risk." (PMID 25208225, 2014). "Hence, to conduct a more precise analysis of the association between GSTM1- and GSTT1-null genotypes and endometriosis risk, additional studies with larger sample sizes and involving different ethnicities (especially African) are needed." (PMID 25208225, 2014). "However, the null genotypes of the GSTM1 and GSTT1 genes and the combined GSTM1/GSTT1 gene may be risk factors for endometriosis." (PMID 30617052, 2019). "Null genotypes of GSTM1 and GSTT1 could act as biomarkers of endometriosis susceptibility." (PMID 25208225, 2014). "The activation of estrogen receptors in endometriosis can also be implemented indirectly via an abnormal activity of CYP1A1, CYP19, and GSTM1 polymorphic enzymes, which increase the level of P450 aromatase and estrogen production." (PMID 33153202, 2020). "Summary of studies which evaluated the GSTM1, GSTT1 and GSTP1 variations in endometriosis." (PMID 27351025, 2016). "Moreover, future studies should further evaluate potential gene-to-gene and gene-to-environment interactions to clarify the role of the GSTM1 and GSTT1 genes in endometriosis." (PMID 25208225, 2014).